BRCA1 (BRCA1 DNA repair associated)
Diseases named in the same sentence as BRCA1 in open-access papers (continued):
Sharing a sentence is not in itself a finding about the gene and the disease.
ischemic stroke (3 papers, 2019 to 2023). A stroke disorder caused by obstruction of blood flow to the brain, due to thrombotic (local blood clot formation) or embolic (due to a blood clot or other material traveling from another site) event. "Differentially expressed analysis showed that POLR2F, BRCA1, and TRIM21 in this RBPS were associated with ischemic stroke." (PMID 36118697, 2022). "Further, the transplantation of BRCA1-transfected NSCs into mice with ischemic stroke increased brain-derived neurotropic factor and nerve growth factor expression in the brain and elicited neurological function improvement." (PMID 31073355, 2019). "Our findings indicate that modification with BRCA1 could enhance the efficacy of NSCs transplantation in ischemic stroke." (PMID 31073355, 2019). "Modification of BRCA1 could enhance the effectiveness of NSCs transplantation in ischemic stroke." (PMID 31073355, 2019). "Overexpression of BRCA1 in neural stem cells (NSCs) reduces apoptosis and oxidative stress after the oxygen-glucose deprivation/reoxygenation (OGD/R) insert, stimulating their proliferation, thus improving the therapeutic effects of NSC transplantation in cases of ischemic stroke." (PMID 36118697, 2022).
male infertility (3 papers, 2017 to 2025). The inability of the male to effect fertilization of an ovum after a specified period of unprotected intercourse. "Thus, the concurrent presence of male infertility and LCT may be linked to RBBP7 mutations affecting key genome stability factors, such as histone H4 and BRCA1." (PMID 37843278, 2023).
myeloid neoplasm (3 papers, 2019 to 2025). Proliferation of myeloid cells originating from a primitive stem cell.
myeloma (3 papers, 2020 to 2025). "We further analyzed primary myeloma cells from 20 treated patients and found a positive correlation between the cGAS expression and BRCA1, SEI1, or PD‐L1 expression." (PMID 40135791, 2025). "Our results indicate the regulation of NSD2 stability by BRCA1-mediated ubiquitination as a potential therapeutic target process in multiple myeloma." (PMID 32826945, 2020). "Thus regulation of MMSET/NSD2 stability BRCA1-mediated ubiquitination could be explored for potential therapeutic interventions in multiple myeloma." (PMID 32826945, 2020). "Finally, to assess the clinical relevance of chemotherapy and PD‐L1 expression in myeloma patients, qPCR analysis confirmed the upregulation of BRCA1, cGAS, SEI1, and PD‐L1 expressions in primary myeloma cells isolated from the bone marrow aspirates of 20 myeloma patients before and after treatment." (PMID 40135791, 2025).
myocardial infarction (3 papers, 2015 to 2017). Gross necrosis of the myocardium, as a result of interruption of the blood supply to the area, as in coronary thrombosis. "In the rat brain, DNA double-strand breaks (DSBs) were induced by ischemia, and BRCA1 which is involved in the repair of DNA DSBs has been shown to be involved in heart function and survival following myocardial infarction." (PMID 25890248, 2015).
neuroendocrine neoplasm (3 papers, 2019 to 2025). Endocrine tumors, also referred to as neuroendocrine tumors (NETs), are defined by a common phenotype which is characterized by the expression of general markers (neuron specific enolase, chromogranin, synaptophysin) and hormone secretion products. "Secondly, P-STS harbour several mutations that are atypical for well-differentiated neuroendocrine tumours and that can influence the radiosensitivity of the cell line, including mutations in BRCA1 and BRCA2." (PMID 30730850, 2019). "Three patients demonstrated pathogenic (class 5) BRCA1 or BRCA2 mutations – one germline-related in a mixed neuroendocrine-non neuroendocrine neoplasm (MiNEN)." (PMID 30717682, 2019). "One patient (patient 3) harbors a germline-related BRCA1 mutation and developed a mixed neuroendocrine-non neuroendocrine neoplasm (MiNEN) in his ileum." (PMID 30717682, 2019).
neurofibromatosis (3 papers, 2020 to 2025). A hereditary neoplastic syndrome in which tumors grow in the nervous system. "Few studies have shown an association with BRCA1 and BRCA2 gene mutations, along with familial syndromes such as neurofibromatosis, Maffucci syndrome, or Klippel-Trenaunay syndrome." (PMID 41181773, 2025).
pancreatitis (3 papers, 2023 to 2024). Inflammation of the pancreas. "They include DNA damage response and DNA repair genes (ATM, BRCA1, BRCA2, and POLQ), pancreatitis gene (SPINK1) and cell apoptosis gene (CASP8)." (PMID 37234870, 2023).
papillary serous carcinoma (3 papers, 2004 to 2020). "Among the 38 patients who underwent a bilateral oophorectomy were 26 BRCA1 mutation carriers, three of whom (3.4 in 100 women-years) developed papillary serous carcinoma of the peritoneum 27, 33 and 70 months after the prophylactic surgery." (PMID 15083174, 2004).
pheochromocytoma (3 papers, 2017 to 2019). "The relationship between pheochromocytomas and BRCA1 and BRCA2 mutations was demonstrated by the detection of mutations in these genes in blood samples from two patients with pheochromocytoma." (PMID 28187001, 2017). "Although no information is available from more detailed studies and a definite conclusion cannot be drawn from a set of only two cases, these findings suggest that an increased risk of pheochromocytomas may be associated with BRCA1 and BRCA2 mutations." (PMID 28187001, 2017).
polycystic ovary syndrome (3 papers, 2024 to 2026). A disorder that manifests as multiple cysts on the ovaries. "In the plasma of individuals with polycystic ovary syndrome (PCOS), it has been observed that BRCA1/2 reversion mutations are present in the ctDNA." (PMID 39492906, 2024).
situ breast cancer (3 papers, 2019 to 2022).
thrombophilia (3 papers, 2019 to 2022). A condition characterized by an abnormally high level of thrombi. "In particular, the main GT category was related to nutrigenomics, celiac disease, thrombophilia, and BRCA1/2." (PMID 33840815, 2022). "The upregulation of TRIM21 and BRCA1 and the downregulation of POLR2F were related to platelet activation and increased coagulation, thus suggesting that an imbalance among these genes may result in a state of hypercoagulation, which could easily lead to an ischemic cerebral infarction." (PMID 36118697, 2022).
thymic lymphoma (3 papers, 2007 to 2024). "In our hands, Brca1−/−53bp1−/− mice were born at around half of the expected frequency and weighed less than their Brca1+/−53bp1−/− littermates, with most succumbing to thymic lymphoma between 12 and 20 weeks of age, consistent with recent reports." (PMID 39227718, 2024). "As MMEJ is highly mutagenic, it is possible that Brca1−/−;Trp53bp1−/− embryos survive at the cost of having increased genomic instability and eventually develop thymic lymphoma." (PMID 32139898, 2020). "Although Brca1−/−;Trp53bp1−/− mice are viable, they have severe genomic instability and eventually develop thymic lymphoma within 7 months." (PMID 32139898, 2020). "Therefore, the combination of defective HR, elevated MMEJ, and compromised cell cycle checkpoint leads to the development of a unique type of thymic lymphoma in Brca1−/−;Trp53bp1−/− mice." (PMID 32139898, 2020). "BRCA1-53BP1 double knockout (DKO) mice have severe genomic instability and G2/M cell cycle checkpoint defects and develop a unique type of thymic lymphoma that is 100% penetrant." (PMID 32139898, 2020). "Although unable to restore HR deficiency, 53BP1 KO partially rescued embryonic lethality of Brca1−/− embryos and no abnormality was observed in the viable Brca1−/−;Trp53bp1−/− mice until they die of thymic lymphoma." (PMID 32139898, 2020). "Interestingly, 100% Brca1−/−;Trp53bp1−/− mice succumbed to thymic lymphoma within 7 months while none of the Trp53bp1−/− mice in the cohort were dead during this period, which is a stronger phenotype than that observed in Brca1ΔC/ΔC;Trp53bp1−/− mice." (PMID 32139898, 2020). "Interestingly, BRCA1-53BP1 DKO mice rapidly develop thymic lymphoma that is 100% penetrant, which is not observed in any BRCA1 mutant mice rescued by 53BP1 KO." (PMID 32139898, 2020).
Tumor Predisposition Syndrome (3 papers, 2015 to 2023). "Breast cancer gene 1 (BRCA1)-Associated Protein Tumor Predisposition Syndrome (BAP1-TPDS) is a relatively newly discovered syndrome that may develop a variety of malignancies, including atypical melanoma resembling Spitz nevi." (PMID 34646590, 2021). "Some 25–55 % of these in-family diseases are attributed to germline mutations of BRCA1 or BRCA2, and approximately 5–10 % to other known tumor predisposition syndromes." (PMID 26109557, 2015).
-related cancer syndrome (2 papers, 2020 to 2025). "One study explored genetic education for BRCA1-related cancer syndrome, MLH1-related cancer syndrome, and HFE-related hemochromatosis." (PMID 40911841, 2025).
acinar cell carcinoma (2 papers, 2015 to 2018). "The development of acinar cell carcinoma was also reported in a patient with a BRCA1 germline mutation." (PMID 25743105, 2015). "In the current study, considering the low incidence of BRCA1-associated acinar cell carcinoma and lacrimal gland tumor, Brca1-mutant mice were found to be a useful model for investigating tumorigenesis of lacrimal gland tumors and preclinical study for testing treatment efficacy." (PMID 30652068, 2018). "In this study, in the cohort of conditional Brca1 knockout mice, we identified several acinic cell carcinomas in the lacrimal gland." (PMID 30652068, 2018). "Then, we performed target sequencing analyses for the entire coding regions of BRCA1, BRCA2, FAT1, and FAT4 via a semiconductor sequencer in an additional 4 cases of acinar cell carcinoma, using archival formalin-fixed and paraffin-embedded (FFPE) tissues." (PMID 25743105, 2015).
adenocarcinoma of the uterine cervix (2 papers, 2022 to 2024). "As here reported, the BRCA testing revealed the presence of the unclassified BRCA1 c.5057A>C (p.His1686Pro) variant in the BC affected proband, in her daughter affected by an adenocarcinoma of the uterine cervix, and in a BC affected niece." (PMID 36741700, 2022).
angiosarcoma (2 papers, 2018 to 2025). A malignant tumor arising from the endothelial cells of the blood vessels. "In another study, 3 of 7 cases of radiation-induced angiosarcoma contained BRCA1 or BRCA2 mutations." (PMID 29515789, 2018). "In addition, genes associated with the role of BRCA1 in DNA damage response are commonly altered in all of the current cases of radiation-induced angiosarcoma." (PMID 29515789, 2018).
Arrhythmia (2 papers, 2017 to 2020). Any cardiac rhythm other than the normal sinus rhythm. "In addition, 21 of 232 (9.1%) BRCA1 carriers and 13 of 159 (8.2%) of BRCA2 carriers reported arrhythmias." (PMID 28157161, 2017). "In addition, 9.1% of BRCA1 carriers and 8.2% of BRCA2 carriers reported arrhythmias." (PMID 28157161, 2017).
astrocytoma (2 papers, 2004 to 2015). "Seventeen genes (ABL, APC, APAF1, BRCA1, CSPG2, DAPK1, hMLH1, LKB1, PTEN, p14ARF, p15INK4b, p27KIP1, p57KIP2, RASSF1C, RB1, SURVIVIN, and VHL) displayed a uniformly unmethylated pattern in all the astrocytoma and non-astrocytoma tissues examined." (PMID 15367334, 2004).
Autoimmunity (2 papers, 2012 to 2013). The occurrence of an immune reaction against the organism's own cells or tissues. "These varying mutations of the FMR1 gene have since also proven associated with risk towards autoimmunity and, potentially, BRCA1/BRCA2-associated cancer risks." (PMID 23948096, 2013). "It is also the genotype associated with lowest IVF pregnancy rates, autoimmunity and, likely, BRCA1/2-associated cancer risks." (PMID 23948096, 2013).
B-cell Lymphoma (2 papers, 2022 to 2025). "A proteome profiling carried out on BRCA1-mutated W780 and W0069 cells evidenced that CDDO-Im significantly increases caspase 3 cleavage, increases heat shock protein 70 (HSP70), and decreases in claspin, BIRC5, B-cell Lymphoma-extra-large, and BCL2 associated agonist of cell death." (PMID 40136510, 2025).
bone metastasis (2 papers, 2023). Transfer of a neoplasm from its primary site to bones. "The proportion of patients who had bone metastasis as the only metastatic site was numerically lower in those with BRCA1/2 mutations than without (15.8% vs. 40.3%)." (PMID 36358026, 2023).
Cachexia (2 papers, 2020 to 2024). Severe weight loss, wasting of muscle, loss of appetite, and general debility related to a chronic disease. "While tumor growth in Brca1-def models was monitored for 13 weeks post tumor-cell injection, Bard1-def models could only be monitored for 5 weeks due to the onset of cachexia, as described in our previous studies." (PMID 38956205, 2024). "Knowledge of the specific factors that regulate Zip14 induction in muscle cells in the Bard1‐deficient, orthotopic model could therefore inform new therapeutic opportunities to prevent or reverse cachexia in triple‐negative breast cancer models with disrupted Brca1/Bard1 function." (PMID 32730698, 2020).
cataract (2 papers, 2020 to 2021). Partial or complete opacity of the crystalline lens of one or both eyes that decreases visual acuity and eventually results in blindness. "Indeed, it has been showed that mice homo- and heterozygous for the DNA repair genes ATM, BRCA1 and RAD9 develop cataracts earlier and in greater numbers." (PMID 33303795, 2020).
Cerebral ischemia (2 papers, 2022). Restriction of arterial blood supply to the brain associated with insufficient oxygenation to support the metabolic requirements of the tissue. "In cerebral ischemia/reperfusion (I/R), BRCA1 overexpression can alleviate or prevent nerve injury caused by I/R due to reduced production of reactive oxygen species (ROS) and lipid peroxidation." (PMID 36118697, 2022). "For example, Brca1 can rescue neurons from cerebral ischemia/reperfusion injury." (PMID 36430332, 2022). "Thus, we speculate that Brca1 rescues neurons by affecting precursor cells in cerebral tissue in cerebral ischemia/reperfusion injury." (PMID 36430332, 2022).
Cirrhosis (2 papers, 2024 to 2025). A chronic disorder of the liver in which liver tissue becomes scarred and is partially replaced by regenerative nodules and fibrotic tissue resulting in loss of liver function. "Interestingly, stem-like cells in precancers such as BPH, cirrhosis, and AK exhibited scores similar to those of cancers, even surpassing stemness scores in malignancies (e.g., BRCA1-mut and LP)." (PMID 38645221, 2024).
cognitive decline (2 papers, 2019). "Indeed, a reduction in the DNA repair protein breast cancer type 1 susceptibility protein (BRCA1) expression has been reported in the brains of human AD patients as well as an amyloid mouse model of AD, and depletion of BRCA1 is suggested to contribute to the cognitive decline seen in AD." (PMID 31727161, 2019).
colon adenocarcinoma (2 papers, 2012 to 2018). "To this end, we have characterized the ethaRAPTA interaction with DNA, including probing the sequence specific modified DNA structural stability and DNA amplification using the breast cancer suppressor gene 1 (BRCA1) of human breast and colon adenocarcinoma cell lines as models." (PMID 23202946, 2012). "We have characterized the ethaRAPTA interaction with DNA, including probing the sequence specific modified DNA structural stability and DNA amplification using the breast cancer suppressor gene 1 (BRCA1) of human breast and colon adenocarcinoma cell lines as models." (PMID 23202946, 2012).
coronary atherosclerosis (2 papers, 2012 to 2021). Atherosclerosis of the coronary vasculature. "Given its integral role in genomic stability and DNA repair, a similar role in the pathogenesis of coronary atherosclerosis, plaque rupture, and response to ischemic damage may exist for BRCA1/2." (PMID 22809218, 2012).
deficiencies (2 papers, 2023 to 2025). "Given the established efficacy of PARP inhibitors in cancers with BRCA1/2 mutation-related homologous recombination deficiencies (HRD), we explored the therapeutic potential of DAC against cancer cell lines derived from solid tumors harboring HRD mutations." (PMID 39930152, 2025). "All TNBC models, irrespective of BRCA1 mutation or epigenetic silencing, presented elevated genetic instability scores (CX2, CX5) shown to be linked with BRCA-deficiency." (PMID 37007122, 2023).
DNA repair deficiency (2 papers, 2017 to 2018). "It has been shown in several publications that BRCA1/2 mutations, which are associated with increased DNA repair deficiency, can be found in at least 10–15% of all TNBCs, especially in those with a high grade and Ki-67." (PMID 30373556, 2018).
ependymoma (2 papers, 2016 to 2023). A WHO grade II, slow growing tumor of children and young adults, usually located intraventricularly. "A germline BRCA1 mutation was discovered in an 18-year-old boy with a rare hepatic tumor and a 17-year-old girl with ependymoma." (PMID 28007021, 2016).
female genital tract cancer (2 papers, 2021 to 2025). "Disease sites of female genital tract cancers of BRCA1/2-associated hereditary breast and ovarian cancer (HBOC) are less understood than non-hereditary cancers." (PMID 33531027, 2021).
herpesvirus infections (2 papers, 2016 to 2023). "Immunodeficiencies in BRCA1 and BRCA2 mutants may allow for the reactivation of latent EBV infections or new herpesvirus infections." (PMID 37241036, 2023).
Hypertension (2 papers, 2022 to 2024). The presence of chronic increased pressure in the systemic arterial system. "One prospective study was underpowered to assess for differences in cardiac dysfunction between groups, excluded participants with hypertension or those who received trastuzumab, and did not demonstrate expected LVEF declines among BRCA1/2 mutation carriers receiving anthracyclines." (PMID 35242827, 2022).
Immunodeficiencies (2 papers, 2020 to 2023). "Mouse studies have shown that 53BP1 loss causes growth retardation, immunodeficiency and radio-sensitivity, while preventing the chromosomal aberrations seen in BRCA1 null animals, stressing the importance of BRCA1-dependent removal of 53BP1 to mediate the transition from NHEJ to HR14,16,17." (PMID 32948765, 2020).
ischemia (2 papers, 2015 to 2017). A hypoperfusion of the BLOOD through an organ or tissue caused by a PATHOLOGIC CONSTRICTION or obstruction of its BLOOD VESSELS, or an absence of BLOOD CIRCULATION. "In support of this theory, murine studies conducted with cardiac myocytes revealed that wild-type BRCA1 is essential to limiting apoptosis and improving cardiac function in response to genotoxic stress (doxorubicin) and oxidative stress (ischemia)." (PMID 28157161, 2017).
latent infection (2 papers, 2016 to 2024). "We also observed similar findings and in addition, demonstrate the interactions of cGAS with H2B, IFI16, BRCA1, and STING in the cytoplasm of cells during de novo infection as well as in latent infection." (PMID 27764250, 2016). "Moreover, actively proliferating cell subsets in early and latent infection contexts have EZH2, TCF3, and BRCA1 expression signatures as observed in proliferating DZ B cells in vivo." (PMID 38059622, 2024). "Nevertheless, these findings suggest that IFI16, H2B, BRCA1, cGAS and STING associate in the cytoplasm during KSHV de novo and latent infection that is independent of ASC." (PMID 27764250, 2016).
liposarcoma (2 papers, 2020 to 2021). A usually painless malignant tumor that arises from adipose tissue. "Signature 3, the canonical double-strand break signature linked to mutations in BRCA1 or BRCA2 or to a BRCAness phenotype, was more pronounced in cases with chromothripsis in liposarcoma." (PMID 32385320, 2020).